SCARNA4 (small Cajal body-specific RNA 4)
Synonyms: ACA26
Gene: Small Cajal body-specific RNA gene on chromosome 1 (155,925,958 to 155,926,085, reverse strand). Ensembl gene ENSG00000280466.
Gene Ontology:
Biological process: RNA processing
Cellular component: Cajal body; nucleolus
Homologues: Paralogues in human: SCARNA4 (100% identical).
Diseases named in the same sentence as SCARNA4 in open-access papers:
SCARNA4 is named in the same sentence as 1 disease in open-access papers, as found by Europe PMC text mining. Sharing a sentence is not in itself a finding about the gene and the disease. The quoted sentences say what the papers report.
cancer (1 paper, 2024). A tumor composed of atypical neoplastic, often pleomorphic cells that invade other tissues. "Therefore, we believe that SNORD16, SNORD73B, SCARNA4, and SNORD49B are significant contributors to the development and spread of cancer, even if additional study is required to elucidate their potential molecular pathways." (PMID 38311725, 2024).